P2RX7 (purinergic receptor P2X 7)
Diseases named in the same sentence as P2RX7 in open-access papers (continued):
Sharing a sentence is not in itself a finding about the gene and the disease.
Obesity (12 papers, 2008 to 2025). Accumulation of substantial excess body fat. "We also show an HFD‐induced expression of P2rx7, a modulator of cell senescence increased in obesity, restricted to eWAT." (PMID 34278707, 2021). "One possible interpretation of the finding that P2rx7 is dispensable for the development of diet-induced obesity and insulin resistance is that other members of the P2X receptor family alone or in combination with other members may play a more important role in these processes." (PMID 33025427, 2020).
osteosarcoma (12 papers, 2011 to 2025). A usually aggressive malignant bone-forming mesenchymal neoplasm, predominantly affecting adolescents and young adults. "P2RX7 plays a key role in metabolic reprogramming and osteosarcoma progression via increasing c-Myc stability." (PMID 36803784, 2023). "We demonstrated that P2RX7 significantly promotes glucose metabolism in osteosarcoma via upregulating the expression of genes related to glucose metabolism." (PMID 36803784, 2023). "Inhibition of glucose metabolism largely abolishes the ability of P2RX7 to promote osteosarcoma progression." (PMID 36803784, 2023). "Furthermore, P2RX7 promotes osteosarcoma growth and metastasis through metabolic reprogramming in a predominantly c-Myc-dependent manner." (PMID 36803784, 2023). "In our previous study, P2RX7 has been identified as an oncogene in osteosarcoma." (PMID 36803784, 2023). "However, whether and how P2RX7 promotes osteosarcoma growth and metastasis through metabolic reprogramming remains unexplored." (PMID 36803784, 2023).
autoimmune disease (11 papers, 2015 to 2026). A disorder resulting from loss of function or tissue destruction of an organ or multiple organs, arising from humoral or cellular immune responses of the individual to their own tissue constituents. "Therefore, we hypothesized that P2RX7 deficiency enhances autoimmune disease by increasing the Tfh cell response." (PMID 30949163, 2019). "For example, P2RX7 inhibition would likely enhance those autoimmune diseases that are mediated by auto-Abs and Tfh cells such as is seen here in the K/BxN model and in EAE models reported previously." (PMID 30949163, 2019). "Therefore, P2RX7 has been targeted as a means of developing anti-inflammatory therapies in many autoimmune diseases." (PMID 30949163, 2019). "Thus, we hypothesized that P2RX7 is required to control autoimmune disease by keeping the Tfh cell response in check." (PMID 30949163, 2019).
Cognitive impairment (11 papers, 2015 to 2025). Abnormal cognition is characterized by deficits in thinking, reasoning, or remembering. "Whatever the mechanism, our findings suggest that DMD-associated cognitive impairment could be treated with administration of P2RX7 antagonists." (PMID 26461208, 2015). "Here, we show that genetic deletion of P2rx7 mitigates brain atrophy, tau accumulation and cognitive impairment in PS19 tauopathy mice." (PMID 40678243, 2025). "P2RX7 ablation also reduced blood levels of creatinine kinase (a marker of muscle, heart, and brain injury), cognitive impairment, and bone structure alterations." (PMID 26461208, 2015).
glioblastoma (11 papers, 2017 to 2026). The most malignant astrocytic tumor (WHO grade IV). "In silico analysis showed that the P2RX7 gene is seldom mutated in specimens from glioblastoma multiforme (GBM) patients." (PMID 31448051, 2019). "Furthermore, functional studies have shown that P2RX7, if activated by the agonist BzATP or if overexpressed, promotes growth and migration of glioblastoma cells in vitro and in vivo." (PMID 34067658, 2021).
glomerulonephritis (11 papers, 2013 to 2024). A renal disorder characterized by damage in the glomeruli. "Rat mononuclear phagocytes may be able to utilise an ‘alternative inflammasome’ pathway to produce IL‐1β independently of P2RX7, which may account for the susceptibility of P2RX7 KO rats to inflammation and autoimmunity in glomerulonephritis." (PMID 35239186, 2022). "Several studies suggest the involvement of P2RX7 and IL‐1β in autoimmune and inflammatory diseases, including glomerulonephritis (GN), in both rodents and humans." (PMID 35239186, 2022). "In this study we developed and phenotyped a novel P2RX7 KO rat on a Wistar‐Kyoto (WKY) background and explored the hypothesis that P2RX7 plays a role in experimental models of GN and autoimmunity using three different models of glomerulonephritis and vasculitis." (PMID 35239186, 2022). "We found that deletion of P2RX7 does not protect rats from models of experimental glomerulonephritis or the development of autoimmunity." (PMID 35239186, 2022). "Taken together, these results comprehensively establish that inflammation and autoimmunity in glomerulonephritis is independent of P2RX7 and reveals the off‐target properties of drugs previously known as selective P2RX7 antagonists." (PMID 35239186, 2022).
viral infections (11 papers, 2012 to 2025). "Several studies have suggested that P2RX7 may be involved in the intensification of inflammatory responses late during a disease and may even be required for the viral infection of host cells." (PMID 38299864, 2024). "However, we report for the first time the crucial role of P2RX7 for antigen- specific T cell immunity in a viral infection model." (PMID 38711513, 2024). "Mitochondria and energy metabolism are impacted during viral infection and since the presence of P2RX7 on mitochondrial surfaces of HEK293 hP2RX7 and N13 microglial cells has been shown recently by others, we determined the mitochondrial activity in our feeder cells." (PMID 38711513, 2024). "Interestingly, P2RX7 activation has been found to be both beneficial and detrimental to resolving viral infections." (PMID 33198300, 2020). "In addition, P2RX7 has been demonstrated to play an important role in regulating inflammatory responses during acute viral infection in mouse." (PMID 24796752, 2014).
gastric cancer (10 papers, 2020 to 2025). A primary or metastatic malignant neoplasm involving the stomach. "Recent studies have used P2RX7 as a presumed target for gastric cancer, described its potential association with poor prognosis of gastric cancer, and clarified that P2RX7 in the growth and metastasis of gastric cancer." (PMID 38757752, 2024). "In gastric cancer cells, P2RX7 enhanced the proliferation, migration, and invasion of cancer cells via modulating ERK1/2 and Akt pathways and epithelial–mesenchymal transition." (PMID 41007849, 2025). "On the other hand, abnormal methylation of genes, for example, IGF2, SLC16A2, SOX11, P2RX7, and MYOD1, were identified in H. pylori infection and significantly correlated with gastric cancer and its clinicopathological features." (PMID 41614769, 2025).
lupus (10 papers, 2005 to 2025). "We also show that current genetic mapping indicates that the P2RX7 gene is located within the region defined as lbw3 and is a therefore a strong candidate for being the product of this lupus susceptibility locus." (PMID 15899033, 2005).
acute myeloid leukemia (9 papers, 2020 to 2026). Acute myeloid leukemia (AML) is a group of neoplasms arising from precursor cells committed to the myeloid cell-line differentiation.
Arthritis (9 papers, 2005 to 2025). Inflammation of a joint. "We found that P2RX7 deficiency in the original K/BxN model led to worsened arthritis and higher auto-Ab titers." (PMID 30949163, 2019). "We further found that T cell-intrinsic P2RX7 ablation is sufficient to generate an autoimmune-exacerbation effect similar to that of P2RX7 deficiency in the whole mouse, i.e., an increase in arthritis, auto-Ab titers, and PP Tfh cell numbers." (PMID 30949163, 2019). "To dissect whether the enhanced Tfh cell response and arthritis severity observed in P2RX7 deficiency of the whole K/BxN mouse is mediated by a T cell-intrinsic effect of P2RX7, we used the K/BxN T cell transfer system." (PMID 30949163, 2019). "Because Tfh cells have been shown to affect the gut microbiota and vice versa, we examined whether a disease enhancing gut microbiota might combine with loss of P2RX7 to induce even greater arthritis development." (PMID 30949163, 2019). "Interestingly, the arthritis enhancement in SFB(–) mice was reproducible simply by deleting P2RX7 in T cells, which led to an enhanced Tfh cell response." (PMID 30949163, 2019). "More studies will be required to determine the exact mechanism of whether and how SFB may inhibit P2RX7 signaling to enhance Tfh cell responses and arthritis development." (PMID 30949163, 2019). "This suggests that P2RX7 deficiency in T cells alone is not enough to inhibit SFB colonization levels, at least in the K/BxN arthritis model." (PMID 30949163, 2019). "We speculate that the lack of arthritis difference between WT and KO groups in the SFB (+) condition could be due to an overlapping effect between SFB and P2RX7 deficiency in enhancing arthritis development." (PMID 30949163, 2019).
lung fibrosis (9 papers, 2013 to 2025). "Another macrophage subpopulation, P2RX7+ macrophages, interacts with ATP to induce lung injury, and neutralizing ATP or blocking P2RX7 can alleviate lung fibrosis." (PMID 41409095, 2025). "Overall, we highlight in this study the ability of the P2RX7/NLRP3/IL-18 pathway in immune cells to inhibit the onset of lung fibrosis by using a positive modulator of P2RX7 that acts selectively in an eATP-rich environment such as fibrotic lung." (PMID 38300690, 2024). "Overall, we show the ability of the immune system to limit lung fibrosis progression by targeting the immunomodulator P2RX7." (PMID 38300690, 2024). "Overall, we show that the P2RX7/NLRP3/IL-18 axis in immune cells is required to limit lung fibrosis progression, highlighting the efficacy in targeting the immune system in this disease." (PMID 38300690, 2024). "In doing so, we initially observed that P2RX7 plays a role in the development of BLM-induced lung fibrosis." (PMID 38300690, 2024). "Activation of P2RX7 with HEI3090 in mice 7 days after BLM administration reduced the development of pulmonary fibrosis, as evidenced by less thickening of alveolar walls and free air space." (PMID 38300690, 2024). "The P2RX7/IL-18/IFN-γ pathway is downregulated in idiopathic pulmonary fibrosis (IPF)." (PMID 38300690, 2024). "We further verified whether the antifibrotic action of HEI3090 depends on the expression of P2RX7 by inducing lung fibrosis in P2rx7−/− mice." (PMID 38300690, 2024). "Even though transcriptomic changes do not always reflect changes in the proteome these encouraging results led us to hypothesize that activation of the P2RX7/IL-18 axis may restrain lung fibrosis progression by promoting an antifibrotic immune microenvironment." (PMID 38300690, 2024). "Hence, treatment with a small activator of P2RX7 may represent a promising strategy to help patients with lung fibrosis." (PMID 38300690, 2024). "High levels of eATP are recognized by the P2X7 receptor (P2RX7) and P2RX7 participates in the establishment of the bleomycin (BLM) lung fibrosis mouse model." (PMID 38300690, 2024). "To test this hypothesis, we enhanced the P2RX7/IL-18 axis in the BLM-induced lung fibrosis mouse model by using HEI3090, a chemical compound described to stimulate immune cells expressing P2RX7 to generate IL-18 in the presence of eATP." (PMID 38300690, 2024). "The P2RX7 signaling pathway is involved in NLRP3 inflammasome activation, and our data are consistent with the findings of a previous report, in which PHMG-p induced lung fibrosis and pulmonary inflammation through activation of the NLRP3 inflammasome in mouse lung tissue." (PMID 31878359, 2019).
osteoarthritis (9 papers, 2014 to 2024). A noninflammatory degenerative joint disease occurring chiefly in older persons, characterized by degeneration of the articular cartilage, hypertrophy of bone at the margins and changes in the synovial membrane. "Importantly, P2RX7 SNPs have been associated with more or less severe pain scores in patient suffering of post-mastectomy pain and osteoarthritis." (PMID 24934217, 2014). "Similarly, pain sensitivity was linked to P2RX7 gene polymorphisms in women with post-mastectomy pain (PMP) and osteoarthritis (OA), with those carrying the gain-of-function (GOF) Tyr155 allele at rs208294 (H155Y) reporting more pain than carriers of the His155 allele." (PMID 24934217, 2014).
schizophrenia (9 papers, 2012 to 2025). A major psychotic disorder characterized by abnormalities in the perception or expression of reality. "Despite biological plausibility and shared inflammatory mechanisms, no P2RX7 variants have shown consistent, genome-wide significant associations with schizophrenia yet." (PMID 40713568, 2025). "We found dysregulation of multiple transcripts whose human orthologs are associated with BPD and other psychiatric disorders including schizophrenia and ADHD, including: Epor, Smarca4, Cmklr1, Cat, Tac1, Npsr1, Fhit, and P2rx7." (PMID 22675514, 2012).
Autoimmunity (8 papers, 2005 to 2025). The occurrence of an immune reaction against the organism's own cells or tissues. "However, studies examining the function of P2RX7 in autoimmunity using P2RX7 deficient mouse models suggest a complicated role for P2RX7, as P2RX7 deficiency can either suppress or exaggerate disease phenotypes." (PMID 30949163, 2019). "Our findings here uncover a previously unrecognized functional interplay between miR‐31‐5p and P2RX7 in macrophage polarization, which adds another layer to the complicated regulatory network of miR‐31‐5p in autoimmunity." (PMID 40068094, 2025). "We contend that the P2RX7 KO rat described here provides an opportunity to study models of inflammation and autoimmunity with greater relevance to human disease than using KO mice." (PMID 35239186, 2022). "Understanding the mechanisms by which P2RX7 impacts autoimmunity will provide the knowledge required to properly target P2RX7 for therapeutic purposes." (PMID 30949163, 2019). "We aimed to further elucidate the role of P2RX7 in autoimmunity by using the spontaneous autoimmune arthritis K/BxN model, along with adoptive transfers to limit the effects of P2RX7 deficiency specifically in T cells." (PMID 30949163, 2019). "P2RX7 has been shown to be important in inflammation and fibrosis and may also play a role in autoimmunity." (PMID 35239186, 2022). "P2RX7 may also play a role in the development of autoimmunity; treatment with a P2RX7 antagonist decreased the severity of experimental autoimmune encephalomyelitis (EAE) in mice." (PMID 35239186, 2022). "As P2RX7 may have a role in the development of autoimmunity, or on lung injury, we next investigated the effect of P2RX7 KO in an autoimmune model, EAG." (PMID 35239186, 2022). "Based on these results, we concluded that Treg depletion is not a driving force in the increased autoimmunity in P2RX7 deficiency." (PMID 30949163, 2019). "Thus, the effect of P2RX7 deficiency on Tregs would likely increase Treg cell numbers, and would be unlikely to explain the increase in autoimmunity observed in P2rx7−/−.K/BxN mice." (PMID 30949163, 2019). "Future studies will be required to understand the mechanisms involved in microbiota-mediated autoimmunity in the absence of P2RX7." (PMID 30949163, 2019). "Taken together, these findings, in three experimental models of GN in WKY WT and P2RX7 KO rats, convincingly indicate that P2RX7 is not critical in mediating GN or autoimmunity in the rat and that unlike AZ11657312, A‐438079 at the dose used is mediating its effects via off‐target mechanisms." (PMID 35239186, 2022). "Thus, unlike the anti-inflammatory effect of P2RX7 blockade in innate immunity reported previously, our results indicated that P2RX7 deletion in T cells actually enhances autoimmunity by unleashing the Tfh cell response." (PMID 30949163, 2019).
glaucoma (8 papers, 2013 to 2025). Increased pressure in the eyeball due to obstruction of the outflow of aqueous humor. "Several receptors have been described to participate in the inflammasome activation phase, the best known of which is P2RX7 (P2X7), which is significantly up-regulated in patients treated for glaucoma." (PMID 38254630, 2023).
malaria (8 papers, 2012 to 2024). Malaria is a serious and sometimes fatal disease caused by a parasite that commonly infects a certain type of mosquito which feeds on humans. "As an evidence of these effects, P2RX7 is upregulated in CD4+ T cells activated during acute murine malaria caused by Plasmodium chabaudi and promotes membrane pore formation, intense Ca++ influx and IL-2 production, and thus induces a vigorous Th1 response that protects mice from death." (PMID 36993971, 2023). "Because P2RX7 has a fundamental role in the generation of Th1 cells during experimental malaria, we sought to determine the first cellular events through which this molecule supports the Th1 response." (PMID 36993971, 2023). "P2RX7 amplifies the Th1 response to malaria by inducing metabolic reprogramming for aerobic glycolysis, which supplies the anabolic intermediates needed to support rapid CD4+ T cell growth and proliferation." (PMID 36993971, 2023). "Of note, several metabolic-related molecules such as P2rx7 (encoding P2X7) and Entpd1 (encoding CD39) were found to correlate with Th1 and Tfh cell bifurcation in malaria." (PMID 36845571, 2021). "P2RX7 acts at the beginning of the malaria immune response, before Th1/Tfh polarization, when activated CD4+ T cells constitute a single population that co-expresses T-bet and Bcl6, and contributes exclusively to the differentiation of Th1 cells, without affecting the generation of early Tfh cells." (PMID 36993971, 2023). "We show that P2RX7 induces T-bet expression and aerobic glycolysis in splenic CD4+ T cells that respond to malaria, at a time prior to Th1/Tfh polarization." (PMID 36993971, 2023). "This study describes a sequence of events arising from P2RX7 signaling in CD4+ T cells that respond to Plasmodium infection, which, together with the data published in this malaria experimental model, provides a clear view on the role of this signaling pathway in Th1 differentiation." (PMID 36993971, 2023). "We concluded that P2RX7-mediated metabolic reprogramming of CD4+ T cells for aerobic glycolysis is a general phenomenon, not restricted to malaria, which is a key event for Th1 differentiation." (PMID 36993971, 2023).
type 2 diabetes (7 papers, 2009 to 2025). "The results show that the HTWP-acupuncture alleviation of the TBI-induced coma duration was offset by the i.c.v injection of P2RX7, P2RX3, and TRPV1 antagonists, indicating that P2RX7, P2RX3, and TRPV1 signaling pathways mediate the awakening effect of acupuncture at HTWP." (PMID 33519382, 2020). "Thus, we analyzed the distribution of P2RX7, P2RX3, and TRPV1 in the vPAG of sham and TBI rats without or with HTWP acupuncture treatment using confocal microscopy to verify that HTWP acupuncture regulates the expression of these receptors in the vPAG to reduce coma duration." (PMID 33519382, 2020).
dry eye (6 papers, 2020 to 2025). "As demonstrated by the results obtained both in vivo and in vitro, miR‐31‐5p is implicated in the pathogenesis of autoimmune dry eye by facilitating M1 macrophage polarization via targeting P2RX7, we next aim to validate these results using samples from SS dry eye patients." (PMID 40068094, 2025).